IL26 (interleukin 26)
Diseases named in the same sentence as IL26 in open-access papers (continued):
Sharing a sentence is not in itself a finding about the gene and the disease.
allergic rhinitis (2 papers, 2019 to 2024). Inflammation of the nasal mucous membranes caused by an IgE-mediated response to external allergens. "Additionally, IL-26 and IL-17 A were increased in dog allergen-sensitized subjects with a history of allergic rhinitis or a history of at least one previously documented food allergy." (PMID 38622712, 2024). "Moreover, systemic IL-26 and IL-17 A concentrations amongst allergen-sensitized children were not clearly different with respect to other allergic manifestations, namely eczema, allergic rhinitis, or a history of one or more food allergies." (PMID 38622712, 2024). "To assess this, we compared systemic concentrations of both IL-26 and IL-17 A in those with and without allergic asthma, eczema, allergic rhinitis, or one or more documented food allergies." (PMID 38622712, 2024).
anaplastic large cell lymphoma (2 papers, 2021). Anaplastic large cell lymphoma (ALCL) is a rare and aggressive peripheral T-cell non-Hodgkin lymphoma, belonging to the group of CD30-positive lymphoproliferative disorders, which affects lymph nodes and extranodal sites. "Downregulated IL26 promotes anaplastic large cell lymphoma cell growth and survival." (PMID 33885377, 2021).
bacterial pneumonia (2 papers, 2021 to 2023). Acute infection of the lung parenchyma caused by bacteria (e.g., Streptococcus pneumoniae, Haemophilus influenzae, Chlamydia pneumoniae, Mycoplasma pneumoniae, and Legionella pneumophila). "We did this by quantifying protein concentrations of IL-26 in lower airway samples from patients with bacterial pneumonia and characterized their relationship with leukocyte and neutrophil concentrations in peripheral blood." (PMID 34777376, 2021). "We observed markedly increased concentrations of IL-26 in lower airway samples from patients with bacterial pneumonia and these correlated with blood neutrophil concentrations." (PMID 34777376, 2021). "To determine whether IL-26 is involved in the immune response during bacterial pneumonia, we quantified extracellular concentrations of IL-26 in lower airway (BAL & BW) samples from patients with bacterial pneumonia." (PMID 34777376, 2021). "To evaluate our hypothesis, we investigated the involvement of IL-26 in bacterial pneumonia in human subjects and the immunological mechanisms behind this involvement." (PMID 34777376, 2021). "The herein described “opposing” associations between local IL-26 and leukocyte and neutrophil concentrations in the blood from patients with bacterial pneumonia and from control subjects, respectively, represent truly novel findings." (PMID 34777376, 2021). "In addition, we have demonstrated the involvement of IL-26 in human bacterial pneumonia and provided confirming evidence that IL-26 exerts direct antibacterial effects, resembling those of an antimicrobial peptide, thereby forwarding IL-26 as a kinocidin." (PMID 37234157, 2023). "Thus, these novel findings on neutrophils and A549 cells, as well as the confirmatory finding on MDM, forward locally accumulated neutrophils, macrophages, and alveolar type II cells as potentially important sources of extracellular IL-26 protein in bacterial pneumonia." (PMID 34777376, 2021).
Behçet's disease (2 papers, 2019 to 2024). "Increased levels of IL-26 are also detected in the sera of patients suffering from Behçet's disease, a rare auto-inflammatory disorder with manifestations of vasculitis; in this context, IL-26 levels correlate with disease severity and it accumulates in inflammatory lesions." (PMID 30809226, 2019).
chronic bronchitis (2 papers, 2018 to 2022). A type of chronic obstructive pulmonary disease characterized by chronic inflammation in the bronchial tree that results in edema, mucus production, obstruction, and reduced airflow to and from the lung alveoli. "Now, given the detected association of IL-26 with growth of pathogenic bacteria, and with chronic bronchitis, we subsequently excluded the particular subjects with these conditions amongst the smokers with or without COPD in the COSMIC cohort." (PMID 29780024, 2018). "Extracellular IL-26 was further increased in long-term smokers with exacerbations of COPD (IS samples), with chronic bronchitis (BAL samples ) or with colonization by pathogenic bacteria (IS and BW samples)." (PMID 29780024, 2018). "Thus, our original observations argue that local extracellular IL-26 protein is increased by long-term smoking per se, with additional enhancement during exacerbations of COPD, in chronic bronchitis and during colonization by pathogenic bacteria." (PMID 29780024, 2018). "The findings of the present study also indicate that there is a further increase in local IL-26 in pulmonary morbidities amongst long-term tobacco smokers, such as chronic bronchitis and COPD exacerbations, as well as in subjects colonized by pathogenic bacteria." (PMID 29780024, 2018). "In this review, we aim to discuss the current role of IL-26 in the lung, with an emphasis on systemic inflammation in patients suffering from COPD and chronic bronchitis." (PMID 36294822, 2022). "These remarkable effects underline the necessity of a better understating of the biological behavior of IL-26 and its role in the pathophysiology and disease burden in several smoking-related airway inflammatory disorders, such as COPD and chronic bronchitis." (PMID 36294822, 2022). "Therefore, it is important to recall that, although the growth of pathogenic bacteria, chronic bronchitis as well as exacerbations of COPD are associated with an increase in local IL-26, this does not undermine the conclusion that long-term tobacco smoking per se does enhance IL-26 in the airways." (PMID 29780024, 2018). "In contrast, we found that in the pooled group of smokers with or without COPD, those with chronic bronchitis displayed a higher average extracellular concentration of IL-26 in BAL samples compared with those without chronic bronchitis." (PMID 29780024, 2018). "Third, we observed that smokers with or without COPD, who also have chronic bronchitis, displayed an increased average concentration of IL-26 in BAL samples, in comparison with those who did not have chronic bronchitis." (PMID 29780024, 2018). "In our current study, we observed that smokers with or without COPD who have chronic bronchitis display an increased average extracellular concentration of IL-26 in BAL samples." (PMID 29780024, 2018). "Here, we hypothesized that the neutrophil-mobilizing cytokine interleukin (IL)-26 (IL-26) is involved in airway inflammation amongst long-term tobacco smokers with or without COPD, chronic bronchitis or colonization by pathogenic bacteria." (PMID 29780024, 2018).
colon carcinoma (2 papers, 2013 to 2021). "In order to ensure high quality and functionality, we used self-produced IL-26 which was functionally tested for STAT3 activation in a colonic carcinoma cell line." (PMID 34733265, 2021). "IL-26 treatment of the colon carcinoma cell line HT-29 slightly decreased cell proliferation and enhanced IL-8 and tumor necrosis factor α secretion and suppressor of cytokine signalling-3 (SOCS3) transcription." (PMID 23875025, 2013). "Further, we stably expressed IL-20R1 in the colon carcinoma cell line HT-29 rendering this cell line responsive to IL-26." (PMID 23875025, 2013). "The HT-29 colon carcinoma cell line used in our laboratory does not express an endogenous functional IL-26R and induces only minimal STAT3 phosphorylation after IL-26 stimulation." (PMID 23875025, 2013).
colorectal cancer (2 papers, 2021 to 2025). A primary or metastatic malignant neoplasm that affects the colon or rectum. "To date, investigations into IL-26 as a biomarker have been conducted in breast cancer, colorectal cancer, pancreatic ductal adenocarcinoma, and HCC." (PMID 41516201, 2025). "In contrast, increased IL-26 expression levels in colorectal cancer were related to good prognosis." (PMID 41516201, 2025). "A recent study of patients with colorectal cancer found significantly higher IL-26 RNA and protein levels in the non-metastatic group than in the metastatic group." (PMID 41516201, 2025).
liver inflammation (2 papers, 2019 to 2024). "In HCV infection, the serum levels of IL-26 were enhanced in chronically HCV-infected patients, mainly in those with severe liver inflammation." (PMID 31464651, 2019).
lupus (2 papers, 2021 to 2022). "We aimed to investigate IL-26 levels in patients with systemic lupus erythematosus (SLE)." (PMID 34054830, 2021). "Here, we report that the levels of IL-26 are higher in SLE patients than in healthy subjects and that patients with active lupus have higher IL-26 levels than those with inactive disease." (PMID 34054830, 2021).
multiple sclerosis (2 papers, 2022 to 2023). A progressive autoimmune disorder affecting the central nervous system resulting in demyelination. "A risk locus containing IL26 and single-nucleotide polymorphisms within the IL26 gene region have been associated with multiple sclerosis, highlighting the fact that IL-26 may be involved in driving TH17 cell–associated inflammatory activity." (PMID 35795664, 2022).
Obesity (2 papers, 2021 to 2024). Accumulation of substantial excess body fat. "Of note, given that increasing levels of both IL-26 and IL-17 A in induced sputum have been independently associated with obesity, we assessed each cytokine in normal weight subjects as compared with overweight subjects." (PMID 38622712, 2024). "Inflammatory arthritis is associated with high serum and synovial fluid levels of IL-26, obesity, and disease activity." (PMID 34572149, 2021). "The current study supports the idea that obesity, often associated with higher circulating saturated FFA levels, can enhance joint destruction in patients with inflammatory arthritis and high IL26 levels." (PMID 34572149, 2021).
pneumonia (2 papers, 2019 to 2021). An acute, acute and chronic, or chronic inflammation focally or diffusely affecting the lung parenchyma, caused by an infection in one or both of the lungs (by bacteria, viruses, fungi, or mycoplasma.). "Thus, IL-26 displays both diagnostic and therapeutic potential in pneumonia and deserves to be further evaluated in these respects." (PMID 34777376, 2021). "The investigated patients with pneumonia displayed substantially increased IL-26 concentrations in two types of lower airway samples, including BAL and BW samples." (PMID 34777376, 2021). "Given that there is overwhelming evidence showing that there is accumulation of leukocytes and neutrophils in human lungs during pneumonia, our finding is suggestive of IL-26 being involved in the mechanisms behind this accumulation." (PMID 34777376, 2021). "First, we observed that the median extracellular IL-26 concentration was markedly increased in lower airway samples from patients with pneumonia." (PMID 34777376, 2021). "In summary, the results of this study demonstrate the involvement in pneumonia patients and link local IL-26 to the systemic mobilization of neutrophils in these patients but not in controls." (PMID 34777376, 2021). "Moreover, we observed a strong positive correlation between IL-26 concentrations in BW samples and blood neutrophil concentrations in the pneumonia patients, and a corresponding moderate correlation with blood leukocyte concentrations." (PMID 34777376, 2021). "Second, we observed that the extracellular IL-26 concentrations in lower airway samples correlated in a positive manner with leukocyte and neutrophil concentrations in peripheral blood from patients with pneumonia." (PMID 34777376, 2021). "Moreover, IL-26 in the BW samples from patients with pneumonia displayed a positive correlation with the leukocyte and neutrophil concentrations in blood, and a similar trend was observed in the BAL samples." (PMID 34777376, 2021). "In contrast, there was a trend towards a positive correlation between IL-26 concentrations in BAL samples and blood neutrophil and leukocyte concentrations in the pneumonia patients." (PMID 34777376, 2021). "We found a substantial increase in the average extracellular protein concentration of IL-26 in the BAL and BW samples from pneumonia patients compared to corresponding control samples (66-fold in the BAL & 52-fold in the BW samples)." (PMID 34777376, 2021). "In addition, we found that the IL-26 concentrations in BW samples correlated in a negative manner with the duration of symptoms in pneumonia patients and there was a trend in the same direction for the IL-26 concentrations in BAL samples." (PMID 34777376, 2021). "However, in contrast to the pneumonia patients, we found that IL-26 concentrations in BAL correlated in a negative manner with leukocyte and neutrophil concentrations in the blood of control subjects, and the same trend was observed in BW samples." (PMID 34777376, 2021).
Pruritus (2 papers, 2020 to 2023). Pruritus is an itch or a sensation that makes a person want to scratch. "It was shown that the expression of genes encoding inflammatory mediators such as CCL4, CCL7, CCL8, CCL20, interleukin-19 (IL-19), IL-20, IL-26, IL-36A, IL-36G, and TNF-α) was unique to psoriatic skin with pruritus." (PMID 37834183, 2023).
pustular psoriasis (2 papers, 2024 to 2025). "In pustular psoriasis, neutrophil-derived IL-26 drives the pathogenic autoinflammation process by inducing the expression of IL-1 cytokines and chemokines that further recruit neutrophils." (PMID 38448036, 2024). "In conclusion, our work identifies constitutive IL-26 expression by neutrophils and demonstrates the role of high levels of IL-26 released by neutrophils in triggering the pathogenic autoinflammation gene program in pustular psoriasis." (PMID 38448036, 2024). "Having found that IL-26 released by neutrophils is overexpressed in pustular psoriasis, we sought to investigate whether it is linked to the autoinflammation process in pustular psoriasis." (PMID 38448036, 2024). "Furthermore, IL-26 was detected in association with neutrophil extracellular traps (NETs) either generated in vitro or released in vivo in pustular psoriasis." (PMID 38448036, 2024). "To investigate whether IL-26 is linked to autoinflammation, we compared IL-26 expression in PV (related to autoimmune T cells) with pustular psoriasis (related to autoinflammation)." (PMID 38448036, 2024). "The findings also suggest that neutrophils, which abundantly infiltrate the skin of pustular psoriasis, represent the principal source of IL-26." (PMID 38448036, 2024). "By studying pustular psoriasis, we identify a cascade where neutrophils release IL-26 and trigger skin autoinflammation." (PMID 38448036, 2024). "Our data provide a major advance in understanding the mechanisms that drive autoinflammation and point to IL-26 as a potential target for therapy of pustular psoriasis and potentially other autoinflammation-related diseases." (PMID 38448036, 2024). "We show that this occurs via the ability of IL-26 to activate the IL26R in keratinocytes, and to kill the skin microbiota in pustular psoriasis, leading to the generation of immunogenic IL-26–DNA complexes." (PMID 38448036, 2024). "In pustular psoriasis, neutrophils synthesize and store IL-26." (PMID 41516201, 2025). "Because we have previously shown that IL-26 is also a potent trigger of innate immunity via binding extracellular DNA, we investigated whether extracellular DNA complexed with IL-26 was present in pustular psoriasis." (PMID 38448036, 2024). "Thus our findings identify neutrophils as an important source of IL-26 and point to IL-26 as the key link between neutrophils and a self-sustaining autoinflammation loop in pustular psoriasis." (PMID 38448036, 2024). "They further demonstrated that IL-26 also upregulates other cytokines, such as TNF-α, and neutrophil-attracting chemokines, including CXCL1 and CXCL8, thus promoting leukocyte recruitment and tissue inflammation in pustular psoriasis." (PMID 41516201, 2025). "IL-26 originates mainly from neutrophils and not T cells, and the high levels of neutrophil-derived IL-26 in pustular psoriasis induce expression of IL-1 cytokines and neutrophil-recruiting chemokines by activating both keratinocytes and neutrophils." (PMID 38448036, 2024). "Tissue immunofluorescence confirmed the increased IL-26 expression in pustular psoriasis (PPPP and GPP) and found a predominant association of IL-26 with neutrophils but not T cells." (PMID 38448036, 2024). "IL-26 signals through the IL-26 heterodimer receptor composed of IL10R2 and IL20R1 and predominantly expressed by keratinocytes in both plaque-type and pustular psoriasis." (PMID 38448036, 2024). "Furthermore, skin explants of pustular psoriasis cultured with a neutralizing anti-IL-26 mAb but not anti-IL-17A mAb completely inhibited the expression of CXCL1, CXCL8, and IL1A, confirming the specific role of IL-26 as a driver of pathogenic autoinflammation circuits." (PMID 38448036, 2024).
sarcoidosis (2 papers, 2020 to 2024). Sarcoidosis is a multisystemic disorder of unknown cause characterized by the formation of immune granulomas in involved organs. "A previous study has documented a significant upregulation of IL26 mRNA expressions in tuberculous lymph nodes and cutaneous sarcoidosis tissues." (PMID 39431054, 2024). "Beside the amended gene expression of IL-26, a strongly increased staining for IL-26 protein in the dermal layer of sarcoidosis skin sections was seen." (PMID 33057074, 2020). "In the context of sarcoidosis these results provide new puzzle pieces of the largely unknown pathogenesis of this disease suggesting a role of IL-26 in the activation of moDCs via TLR2 followed by the secretion of TNF-α, an important pathological player and therapeutical target in sarcoidosis." (PMID 33057074, 2020).
vasculitis (2 papers, 2019 to 2021). "IL-26 is also detected in renal arterial SMC in patients with anti-neutrophil cytoplasmic antibodies (ANCA)-associated vasculitis (AAV)." (PMID 30809226, 2019).
viral infections (2 papers, 2013 to 2022). "If such an immunological mechanism does exist, it further implicates IL-26 in antimicrobial host defense in a wider sense, given the risk for bacterial infection that normally follows the damage of mucosal surfaces caused by viral infections." (PMID 36466824, 2022). "We analyzed the in vitro effects of IL-26 on virus infection and replication with recombinant viruses from three different species, the RNA rhabdovirus VSV, and the DNA herpesviruses HCMV and HSV-1." (PMID 23875025, 2013). "The pre-incubation of the VSV supernatant with recombinant IL-26 was much more efficient than the pre-incubation of the target cells and a considerably lower IL-26 concentration was required for enhancing virus infection." (PMID 23875025, 2013). "Thus, IL-26 seems to interfere with the negatively charged surfaces of viruses and target cells and leads to differential effects on virus infection." (PMID 23875025, 2013). "Here, we describe novel IL-26R-independent effects of the human cytokine IL-26 on virus infection." (PMID 23875025, 2013). "The rapid and strong SOCS3 induction could be involved in the IL-26 effect on virus infection by inhibiting the initial IFN response." (PMID 23875025, 2013). "Therefore, a role of IL-26 in virus infection seemed possible." (PMID 23875025, 2013).
acne (1 paper, 2014). An inflammatory process of the sebaceous glands which is characterized by comedones, nodules, papules and/or pustules on the skin. "Furthermore, Th17 cell products IL-17A, IL-22, IL-26, TNF and IL-17 induced chemokines CSF2 and CCL20 were also expressed at higher levels in acne lesions." (PMID 25153527, 2014).